TLR7 (toll like receptor 7)
Diseases named in the same sentence as TLR7 in open-access papers (continued):
Sharing a sentence is not in itself a finding about the gene and the disease.
autoimmune disease (continued). "TLR2, TLR4, TLR7, and TLR9 recognize PAMPs from infectious agents and DAMPs from tissue damage, contributing uniquely to the pathogenesis of specific autoimmune diseases." (PMID 38732254, 2024). "Recent advancements include the discovery of small-molecular antagonists, such as 7f, which exhibits strong on-target potency and selectivity against TLR7 and TLR9, demonstrating efficacy in the preclinical models of autoimmune diseases by oral administration." (PMID 38732254, 2024). "TLRs, such as TLR2, TLR4, TLR7, and TLR9, are involved in this process, and their dysfunction or overexpression in immune cells plays a pivotal role in the pathogenesis of autoimmune diseases." (PMID 38732254, 2024). "Interestingly, CXCL10 release, identified in this investigation as a robust marker of TLR7/8 immune activation, has also been shown to be part of an amplification feedback loop driven by IFNγ and TNFα release from Th1 lymphocytes in a variety of autoimmune diseases." (PMID 35261923, 2022). "Numerous studies suggest that TLR4-, TLR7- and TLR9-mediated abnormal activation of the macrophages, DCs and B cells contributes to the pathogenesis of inflammation and autoimmune diseases." (PMID 34025679, 2021). "Since PKM2 positively regulates the activation of the TLR4/TLR7/TLR9 pathways under in vitro conditions, the effect of PKM2 in relieving the TLR-mediated inflammation and autoimmune diseases was assessed." (PMID 34025679, 2021). "Upon TLR7 stimulation, DN2 B-cells participate in extrafollicular responses in autoimmune disease patients." (PMID 34295332, 2021). "In particular, inappropriate signaling by TLR4, TLR7, and TLR9 induces hyper-activation of the immune system and contributes to numerous pathological conditions like inflammation and autoimmune diseases." (PMID 34025679, 2021). "Current literature also confirms contribution of some escapes genes including CD40L, IRAK-1, TLR7, CXORF21 and XIAP to the female bias of autoimmune diseases especially SLE disease." (PMID 33297945, 2020). "Reviewing present literature for the contribution of some escapes genes including CD40L, IRAK-1, TLR7, CXORF21 and XIAP confirms their primary attributions to the female bias of autoimmune diseases especially SLE disease." (PMID 33297945, 2020). "Currently, a Phase I clinical trial is underway utilizing the TLR-7, − 8 and − 9 antagonist IMO-8400 to reduce systemic inflammatory drivers in autoimmune disease." (PMID 32527277, 2020). "The release of NET results in the emission of alarmins and formation of RNA/DNA complexes serving as costimulatory elements for TLR7/8 and TLR9, thus linking neutrophils to DCs through inducing DC maturation and the promotion of autoimmune diseases." (PMID 32473089, 2020). "Altogether, these studies open the insights to the TLR7 functions in the activation of the cellular immune responses (both CD4+ T cells and CD8+ T cells) and possible roles in the onset or promotion of autoimmune diseases." (PMID 33297945, 2020). "This enhanced TLR7 expression likely contributes to the female bias in SLE and other autoimmune diseases." (PMID 31354711, 2019). "The doubling of Tlr7 expression in BXSB.Yaa males is sufficient to greatly accelerate the mild, late onset SLE-like autoimmune disease observed in females after 1 year of age to a much more acute disease with deaths averaging 6 months of age." (PMID 27050763, 2016). "Together TLR7 and 9 promote SLE progression and further emphasize the importance of nucleic acid signaling in autoimmune disease development." (PMID 23936008, 2013). "Among the intracellular TLRs, TLR7 and TLR9 play a crucial role in the activation of autoreactive B cells, and subsequent development of autoimmune diseases such as SLE." (PMID 23151919, 2012). "The compound is specifically designed to suppress the key cytokines by inhibiting TLR7 and TLR9 activity; however, some autoimmune disease treatments specifically target inhibition of individual cytokines." (PMID 23151919, 2012).
autoimmune disease (continued). "CpG 52364 is a small molecule TLR antagonist specifically developed for TLR7, TLR8, and TLR9 to inhibit progression of SLE and other autoimmune diseases at an early stage by blocking inappropriate TLR activation." (PMID 23151919, 2012). "Intracellularly localized TLR7 participates in APC activation and autoantibody production showing obvious importance in autoimmune diseases." (PMID 21818370, 2011). "For instance, the viral sensor TLR7 escapes XCI and shows higher expression in human B cells, plasmacytoid dendritic cells (pDCs), and monocytes from females, especially in female-biased autoimmune diseases such as SLE." (PMID 40692743, 2025). "On the other hand, abnormal activation of TLR7 and cGAS-STING signaling pathways may trigger inflammatory responses and autoimmune diseases." (PMID 41516215, 2025). "Roles for TLR7, TLR8, and TLR9 in the pathology of such diseases are now well established in humans and mice, and suppression of TLR activation is being pursued therapeutically as a treatment for several autoimmune diseases." (PMID 38780621, 2024). "Given that TLR7, TLR9, and type I IFN are key drivers of murine autoimmune disease, we investigated whether differences in TLR and IFN signaling pathways may underlie the observed ancestry-based differences in immune phenotypes in health and SLE disease." (PMID 37606045, 2023). "Heightened TLR7/8, TLR9, and IFN-α signaling pathways in immune cells from Black individuals support distinct immune phenotypes observed in response to infection, vaccines, and autoimmune disease." (PMID 37606045, 2023). "Likewise, intracellular nucleic-acid can also induce the production of IFN-beta via nuclei-acid sensors signaling pathways, including TLR7/TLR8-MyD88 signaling pathway, TLR3-IFN-beta signaling pathway and so on in autoimmune diseases." (PMID 36994418, 2023). "TLR7 expression and TLR7 rs3853839 (C/G) genotyping can be useful biomarkers in SLE and other autoimmune diseases to help identify patients who might respond well to TLR7 and/or IFN blockade or B cell-targeted therapies." (PMID 31231380, 2019). "In addition, we investigated the expression levels of TLR7 and TLR9 protein as these TLRs are most relevant in the context of autoimmune disease." (PMID 30761150, 2019). "The present study extends our understanding of TIRAP’s membrane association, which could be helpful in designing peptide decoys to block TLR2-, TLR4-, TLR7-, and TLR9-mediated autoimmune diseases." (PMID 29434596, 2018). "However, the dysregulation of TLR7, TLR8, and TLR9 plays a major role in numerous autoimmune diseases." (PMID 28553556, 2017). "Although both TLR7 and TLR9 are involved in autoantibody production to nuclear self-antigens, TLR7 but not TLR9 is required for the development of autoimmune disease in a mouse model." (PMID 28408984, 2017). "The co-engagement of TLR7 and BCR has been shown to promote autoreactive B cell activity indicating that this could contribute to disease symptoms in autoimmune diseases." (PMID 24740301, 2014). "In principle, the signals sent by TLR7 and TLR9 should be very similar, so why are some autoimmune diseases associated with TLR7 but not TLR9?" (PMID 23426937, 2013). "Intracellular TLRs, particularly TLR7 and TLR9, are involved in various autoimmune diseases by sensing immune complexes such as small ribonucleotide proteins comprised of self-nucleotides; an association between inflammation and cancer development has long been appreciated." (PMID 23151919, 2012). "TLR7- and TLR9-mediated cytokines are critical factors in autoimmune disease." (PMID 23151919, 2012). "TLR7, which was not identified in the present study, is located on the X chromosome, and XCI escapes allow it to show higher expression in women compared to men and is associated with a higher incidence of autoimmune diseases in women." (PMID 39891056, 2025). "Mice lacking either the combined TLR7/9 or MYD88 do not develop autoimmune disease." (PMID 31824490, 2019).
autoimmune disease (continued). "Continuous activation and dysregulation of TLR and type I IFN signaling have been speculated to play a part in this signature and pathogenesis of autoimmune disease, and IFN signature positive pSS patients have been shown to have increased expression of TLR7 in certain cell types." (PMID 30846988, 2019). "High levels of TLR2 and TLR4 expression on myeloid DCs and TLRs TLR7 and TLR9 present in pDCs may have specific functions in autoimmune disease in which molecular mimicry or autoantibodies to essential nucleic acids are a potential underlying mechanism for autoimmune disease onset." (PMID 28396662, 2017). "In autoimmune diseases, autoantibodies directed against RNA-binding self-antigens (anti-Ro/SSA and La/SSB), consequently deliver aberrantly exposed extracellular RNA to the endosomal compartment of B cells and pDCs (via the B cell receptor or Fc receptors) and subsequently trigger TLR7 signalling." (PMID 24740301, 2014). "Interestingly, TLR7 have been reported to be expressed by IFN-DC, which could also secrete IFNα following viral stimulation or TLR7-specific stimulation, thus confirming the critical role of this cytokine at the early steps of immune response to pathogens or in autoimmune diseases." (PMID 21586124, 2011).
influenza (147 papers, 2008 to 2026). An acute viral infection of the respiratory tract, occurring in isolated cases, in epidemics, or in pandemics; it is caused by serologically different strains of viruses (influenzaviruses) designated A, B, and C, has a 3-day incubation period, and usually lasts for 3 to 10 days. "While the identification of critical X‐linked genes and immune cells responsible for these sex differences is unclear, there is evidence for some X‐linked genes, such as Tlr7, that contribute to female‐biased protection following influenza infection." (PMID 41574968, 2026). "SE(Trojan-TLR7/8a) ensures cross-protection against diverse influenza and SARS-CoV-2 variants, providing 100% protection while maintaining a healthy state." (PMID 40562869, 2025). "Concurrently, the lack of observable effects on tumor progression following intratumoral injection of AdjFluVx in TLR7-deficient animals highlights the insignificant role of TLR7 activation in influenza vaccines containing a squalene oil-in-water adjuvant." (PMID 38476365, 2024). "A nanoparticle-based adjuvant incorporating a Toll-like receptor 7 agonist elicits cross-reactive antibodies for both dominant and subdominant epitopes and enhances immune responses against multiple variants of influenza and SARS-CoV-2." (PMID 36717665, 2023). "To determine what role TLR recognition pathways play in the generation of the iABC response to influenza infection, we infected TLR7 and TLR9 deficient aged mice and compared their responses to WT aged and young mice at 14 dpi." (PMID 36056604, 2022). "It has been established that macrophages of TLR7-deficient mice destroyed a higher number of bacteria in influenza infection." (PMID 31513620, 2019). "In accordance, mice deficient for TLR3 and TLR7 (tlr3/tlr7−/−) or the common TLR adapter MyD88 (myd88−/−) demonstrated an increased lethality upon infection with influenza." (PMID 23483993, 2013). "Here, we used a protease deficient mouse model to show the in vivo importance of TLR7 processing in influenza infection." (PMID 22916010, 2012). "However, all the mice immunized with SE(Trojan-TLR7/8a) demonstrated complete protection against diverse influenza subtypes, with rapid reversal of body weight loss and notably, no weight loss upon challenge with H1N1." (PMID 40562869, 2025). "While inflammasome deficiency was detrimental during Influenza infection when compared with wild-type mice, abrogating inflammasome signaling prevented Influenza-induced lethality in Tlr7-/-Mavs-/- mice that are impaired in mounting type I IFN responses to Influenza." (PMID 31017981, 2019). "Influenza has also been shown to be internalized by platelets and its vRNA is recognized by TLR7 leading to NETosis which is essential to initiate an immune response, but dysregulation of the process can increase the risk for thrombotic outcomes." (PMID 40825056, 2025). "Imiquimod, a Toll-like receptor 7 (TLR7) agonist, has shown efficacy in murine models of influenza and respiratory syncytial virus (RSV)." (PMID 40573392, 2025). "Recognition of viral single-stranded RNA (e.g., from HIV or influenza) via TLR7 induces release of α-granule contents, CD40L, and P-selectin, also enhancing platelet-neutrophil aggregation and NET formation." (PMID 40692784, 2025). "Nanoparticle adjuvants, with TLR7 as their main component, have been reported to significantly enhance immune responses against influenza and severe acute respiratory syndrome coronavirus type 2." (PMID 39973927, 2025). "Studies have demonstrated that Yinqiao Powder exerts antiviral effects against influenza and mitigates inflammation by modulating the TLR7/NF-κB signaling pathway." (PMID 40474974, 2025). "Building on the success of TLR4 agonists in enhancing influenza vaccine efficacy, attention turned toward TLR7 agonists for their unique ability to activate antiviral innate immunity." (PMID 41012165, 2025).
influenza (continued). "Following the discovery that seasonal influenza vaccinations activate TLRs in vitro, we focused on establishing TLR7’s role in B16 melanoma tumor development after therapy." (PMID 38476365, 2024). "In summary, this work introduces an effective and biocompatible SNP-based co-delivery platform that enhances the immunogenicity of TLR7/8 agonist-adjuvanted subunit influenza vaccines." (PMID 38258117, 2024). "Their work showed that IFI27 is upregulated by TLR7 in plasmacytoid dendritic cells, more responsive to influenza virus than bacteria, and confirmed its expression in influenza patients through multiple patient cohorts." (PMID 39282474, 2024). "MXSGD and SJZD exhibit synergistic effects in the treatment of influenza, as evidenced by the inhibition of TLR7 and NLRP3 inflammatory pathways early in the infection and facilitation of the response later." (PMID 39221016, 2024). "In rodent models of influenza infection, TRL3- and TLR7-deficient mice are unable to control viral replication and succumb to the disease." (PMID 38835761, 2024). "Supporting the significance of this observation, activation of NOX2 in mice undergoing infection with influenza, a pathogen known to activate TLR7, suppressed proinflammatory cytokine production and reduced antibody production." (PMID 39042716, 2024). "The regulation of TLR7/NF-κB signaling pathway by Guizhi-and-Mahuang decoction is likely to play an important role in the treatment of influenza-induced viral pneumonia." (PMID 37089926, 2023). "The TLR7-NP adjuvant presented in this study not only holds great potential for developing more potent vaccines against influenza strains or other viruses, but also provides a useful tool for understanding the complexities of immune regulation." (PMID 36717665, 2023). "A liposomal formulation containing TLR4 and TLR7 agonists was also shown to be an effective mucosal adjuvant for an influenza vaccine in mice." (PMID 37179389, 2023). "Here, we report the development of a subunit COVID-19 vaccine based on recombinant SARS-CoV-2 RBD proteins produced in yeast that are displayed on influenza virosomes acting as antigen carriers, together with membrane anchored 3M-052 as TLR7/8 agonist." (PMID 36977691, 2023). "The inhibition of ‘cytokine storm’ via the regulation of TLR7/MyD88 signaling pathway was suggested as a potential mechanism of FFYH against influenza pneumonia." (PMID 37089926, 2023). "Our results illustrate the potential role of TLR7–8 gene as key regulators in immunogenicity of seasonal influenza vaccine." (PMID 36804941, 2023). "A recent study reported that TLR7-nanoparticle (TLR7-NP)-adjuvanted influenza and SARS-CoV-2 subunit vaccines induced broad neutralizing antibodies in a mouse model, which protected against respective multiple viral variants." (PMID 38179453, 2023). "We further demonstrate that TLR7-NP-adjuvanted influenza and SARS-CoV-2 subunit vaccines induced high levels of cross-reactive antibody responses to multiple heterologous viral variants." (PMID 36717665, 2023). "Previous studies have found that a decline in influenza-induced production of interferon (IFN)-α in older adults is associated with defective TLR signaling, specifically TLR7." (PMID 37501123, 2023). "This TLR7-NP-adjuvanted influenza subunit vaccine successfully protects mice against viral challenge of a different strain." (PMID 36717665, 2023). "Remarkably, 80% of mice immunized with TLR7-NP-adjuvanted HK68 HA generated antibodies at week 2 against HA from H7N9 A/Shanghai/02/2013 (SH13), a highly pathogenic influenza viral variant from a different subtype." (PMID 36717665, 2023). "We next immunized mice with TLR7-NP- or TLR7–alum-adjuvanted H3 HA from influenza strain A/Hong Kong/1/1968 (HK68), a group 2 influenza viral variant, and examined antibodies against HAs from heterologous strains at week 2 and week 5 post-immunization." (PMID 36717665, 2023).